ITGB6 (integrin subunit beta 6)
Diseases named in the same sentence as ITGB6 in open-access papers (continued):
Sharing a sentence is not in itself a finding about the gene and the disease.
tumor (continued). "ITGB6 regulates epithelial remodeling during development, tissue repair, and tumor formation." (PMID 39356055, 2024). "Furthermore, we evaluated the possible link between the ECMGs and the tumor stage of PAAD, and 8 ECMGs (i.e. FN1, LAMA3, ITGB6, ITGB4, ITGA2, LAMC2, COL11A1, LAMB3) were detected to be significantly associated with tumor stage." (PMID 36311789, 2022). "It has been demonstrated that ITGB6 participated in almost every step during tumor metastasis." (PMID 34796117, 2021). "To date, few articles have stated the role of ITGB6-mediated TGFβ activation in tumor progression." (PMID 34621667, 2021). "Further results also preliminary confirmed that serum ITGB6 levels might serve as a potential biomarker for tumor surveillance and monitoring of tumor recurrence during follow up." (PMID 34796117, 2021). "Rebounded high serum ITGB6 expression may indicate tumor recurrence and a sustained high serum ITGB6 level might represent poor prognosis." (PMID 34796117, 2021). "In addition, the serum expression of ITGB6 decreased significantly after radical surgery, and a new rise in serum ITGB6 expression indicated tumor recurrence or progression." (PMID 34796117, 2021). "As the role of C/EBPα was reported to act as tumor suppressor in several tumor types, including head and neck squamous cell cancers, we initially hypothesized that C/EBPα might repress ITGB6 transcription in OSCC cells." (PMID 25816241, 2015). "Additionally, ITGB6‐expressing tumour cells are enriched in colorectal cancer liver metastases." (PMID 40488391, 2025). "Hence, ITGB6 represents a potential target, which may be exploited for clinical tumor imaging, therapy, theranostics, and as a prognostic marker, potentially resulting in an earlier diagnosis and intervention." (PMID 38890650, 2024). "Thus, HN ITGB6KO may serve as a valuable cell model for future investigations of the tumor-biological effects of ITGB6 in OSCC." (PMID 38890650, 2024). "Moreover, the prognostic signature based on ITGB1, ITGB4, ITGB5 and ITGB6 may facilitate clinicians to identify more aggressive and immunosuppressive tumours and make more individually appropriate therapeutic decisions." (PMID 33073486, 2020). "To further explore the functional role of integrin αvβ6 in the adhesion of tumour cells to EC, we employed CRISPR/Cas9 technology to establish an ITGB6 knockout (KO) cell line, based on the method outlined previously." (PMID 40488391, 2025). "The correlation between inhibition of tumor cell growth and the expression of NECTIN2, ITGB6, and NECTIN1 genes warrants their further investigation as potential biomarkers for oHSV1-FLT3L therapy." (PMID 40955425, 2025). "We observed a high variability in susceptibility to oHSV1-FLT3L infection between the distinct cancer cell lines and found that there was a correlation between the inhibition of tumor cell growth and the expression of NECTIN2, ITGB6, and NECTIN1 genes." (PMID 40955425, 2025). "Initial analyses revealed that mRNA expression of ITGB6, ERBB2, RAB5A, RAB7A, and GDI2 was all significantly higher in tumor tissue in comparison to normal tissue." (PMID 39630893, 2024). "The results showed that the expression levels of ITGA2, ITGB6, LAMA3, LAMB3, and LAMC2 are significantly correlated with the tumor stage of PAAD patients, while the expression levels of COL1A2 are not correlated with the tumor stage of PAAD patients." (PMID 35899199, 2022). "Among the integrin β‐subunits, ITGB1, ITGB2, ITGB4, ITGB5, ITGB6, ITGB7, and ITGB8 were highly expressed in tumour tissues compared with normal tissues." (PMID 34709754, 2021). "ITGB6 was detected in the serum of CRC patients, with a strong predictive index for the onset of metastatic state and tumor recurrence." (PMID 34503224, 2021). "Among these, COL17A1, ITGB6, LAMC2, and S100P were upregulated in tumor tissues, whereas only CHGA was downregulated." (PMID 33015155, 2020).
tumor (continued). "The downregulated MCOLN3 and SLC25A45 with HR < 1 were considered as tumor suppressors, whereas the upregulated COL17A1, CEP55, KLK10, MET, ITGB6, ANKRD22, and ARNTL2 with HR > 1 were regarded as oncogenes." (PMID 31612115, 2019). "The mRNA expression levels of COL17A1, CEP55, KLK10, MET, ITGB6, ANKRD22, and ARNTL2 were significantly increased in PAAD tumor tissue." (PMID 31612115, 2019). "Precisely, the expression of integrin subunit beta 6 (ITGB6), a cell-surface adhesion receptor that mediate cell-ECM interactions, had been related to enhanced cell migration in the context of human neoplasia and wound healing." (PMID 28231262, 2017). "As ITGB6 expression in ESCC was not dependent from tumor grade, it is expected that 68Ga-D0103 PET/CT should perform equally well for patients at any stage." (PMID 40540027, 2025). "Additionally, TENASCIN was frequently observed in the HAS group, with tumor cells in this group interacting with other cells, including tumor cells themselves, via TNC - SDC1/SDC4 or TNC - ITGA8_ITGB1/ITGAV_ITGB6." (PMID 39267750, 2024). "Our RT-qPCR and western blot analysis corroborate with ITGB6 expression in primary tumor samples and its normal counterparts through UALCAN analysis, demonstrating a significant overexpression of this protein in tumor samples compared to controls." (PMID 38951897, 2024). "Gene expression difference analysis manifested that NCF2 was differentially expressed in normal and tumor tissue, rather than ITGB6 and PLAUR." (PMID 36680322, 2023). "A scientific study on ITGB6 knockout animals disclosed that they did not develop any symptoms of malignant or even benign tumours." (PMID 36293202, 2022). "ITGB6 might be involved in the regulation of MMP expression, and contributed to tumor progression via ERK signaling." (PMID 34796117, 2021). "Furthermore, we identified potential molecular targets based on our expression data in NE-low and immune-oasis tumor subsets, including CD70, ANXA1, ITGB6, TP63, IFI27, YBX3 and CXCR2." (PMID 34200100, 2021). "Gains in some of the genes involved in invasive/migratory properties (MGAT5, PKP4, ITGB6), cell cycle progression and regulation of apoptosis (RBMS1), and angiogenesis (NRXN1) may be involved in tumor development and progression." (PMID 26432421, 2015). "After adjustment by tumor purity, we found ITGA1/A5/A8/A11/AD/AV and ITGB1 showed weakly correlation with macrophage markers in OC, ITGA5/A11 and ITGB5 weakly correlated with Treg markers, ITGAD and ITGB6 showed weakly correlation with natural killer cells markers." (PMID 32765584, 2020). "Although methylation of the ITGB6 promoter was not obviously different, the activated histone markers, H3K27ac and H3K4me3, were significantly upregulated in the ITGB6 promoter in the tumor cells." (PMID 33015155, 2020). "Tumour cells with high ITGB6 expression (SW948 and HT‐29 cells) exhibited strong adhesion, whereas ITGB6 nonexpressing cells (LOVO and RKO cells) showed significantly reduced adhesion." (PMID 40488391, 2025).
cancer (29 papers, 2015 to 2026). A tumor composed of atypical neoplastic, often pleomorphic cells that invade other tissues. "Studies have shown that ITGB6 can activate Rac1 signaling in epithelial cells, leading to changes in cell behavior that are associated with cancer progression." (PMID 38344200, 2024). "The advantage of ITGB6 as a target structure lies in its exclusive expression in certain wound healing conditions and cancer, associated with its absence in normal adult epithelia." (PMID 38890650, 2024). "In order to delve deeper into the expression of ITGB6 in cancer, we conducted immunostaining analysis on a total of 198 patient samples." (PMID 38344200, 2024). "Integrin αvβ6 and its subunit integrin beta 6 (ITGB6) were discovered to enhance the invasiveness by providing beneficial effects on downstream pathways promoting the cancer progression." (PMID 38890650, 2024). "ITGB6, respectively αvβ6, is well known for being highly expressed in various cancer types of epithelial origin, such as carcinomas of the lung, breast, stomach, liver, skin, cervix, salivary glands, and oral mucosa." (PMID 38890650, 2024). "ITGB6 can be found in various epithelial tumors and plays a crucial role in the invasion and spread of cancer." (PMID 38344200, 2024). "For example, ITGB6 has been shown to promote cancer cell invasion by activating Rac1 signaling and promoting the formation of cellular protrusions and cell movement." (PMID 38344200, 2024). "Genes potentially associated with cell migration and cancer metastasis included CNTN5, FN1, Integrin Subunit Beta 6 (ITGB6), EPHB1, Unc-5 Netrin Receptor D (UNC5D), SDK1, RADIL, LRRC7, PCDH11X, and ADAMTS9." (PMID 39770638, 2024). "Remarkably, some receptors (ERBB2, ITGA3, and ITGB6) were mainly expressed in cancer cells, and their putative ligands (NRG1 and FN1) were over-expressed in CAFs." (PMID 37879219, 2023). "Integrin subunit beta 6 (ITGB6), as one of Integrins family, has an increased expression level in some biological processes like wound healing, fibrosis, and malignant tumor formation." (PMID 36906533, 2023). "Itgb6 is a membrane-spanning heterodimeric glycoprotein involved in wound healing and the pathogenesis of diseases, including fibrosis and cancer." (PMID 33504014, 2021). "Itgb6 and Fgf13, which are involved in the pathogenesis of diseases such as cancer, exhibited higher expression levels in iF cells than in iTS-P cells." (PMID 33504014, 2021). "ITGB6 is extensively involved in wound healing and the pathogenesis of a variety of diseases, including fibrosis and cancer." (PMID 34660316, 2021). "Integrin alpha-V beta-6 (ITGB6) is a receptor for fibronectin and cytotoxin, and its internalization via clathrin-mediated endocytosis promotes carcinoma cell invasion." (PMID 34200100, 2021). "To understand the transcriptional regulation of the ITGB6 gene in cancer cells, we identified and characterized the human ITGB6 promoter and its activity." (PMID 25816241, 2015). "ITGB6 is a critical subunit of the αvβ6 integrin heterodimer and is involved in regulating the expression of the heterodimer during cancer and wound healing." (PMID 25816241, 2015). "There are several approaches for the usage of ITGB6 and αvβ6 as target structures in cancer." (PMID 38890650, 2024). "Finally, we performed KEGG enrichment analysis of SPP1 signaling pathway receptors (CD44, ITGB1, ITGB6) that were expressed in epithelial cells in 33 cancers, and extracted the intersections of the enriched pathways." (PMID 38648200, 2024). "Additionally, ITGB6 has been shown to promote the acquisition of stem-like properties in cancer cells, allowing them to resist chemotherapy and evade immune surveillance, and this is also mediated through Rac1 signaling." (PMID 38344200, 2024). "ITGB6 is an important integrin subunit for TGFβ signaling pathway and cancer metastasis." (PMID 37898647, 2023).
cancer (continued). "Since there is no available substance under study for the direct inhibition of TNC (source: clue.io), targeting ITGB6 might impede the whole pathway, promoting cancer propagation, making ITGB6 a druggable and biologically valid target." (PMID 36183137, 2022). "The results showed that BCAT1, LY6D, and ITGB6 were significantly overexpressed in cancer tissues." (PMID 34976806, 2021). "Furthermore, we found that some ITGs such as ITGA3, ITGA6 ITGA11, ITGB4, ITGB6, etc. were frequently upregulated in human cancers, whereas ITGs including ITGA1, ITGA7, ITGA8, ITGA9 and ITGB3, etc. were usually downregulated." (PMID 34222028, 2021). "Also, ITGB6 is a known inductor of cell invasion and is a marker of poor prognosis in several cancer types, including BrCa." (PMID 29568399, 2018). "Additionally, SPP1 as a ligand could induce communications of pan T‐cell subtypes to cancer cells specifically in BM or to senescent cancer cells via adhesive receptors ITGAV_ITGB1, ITGAV_ITGB5 and ITGAV_ITGB6." (PMID 39231761, 2025). "Further CellChat analysis revealed that the signaling pathways between cancer cells and identified CAFs (NRG1-ERBB2/4 and FN1-CD44/ITGAV/ITGA3/ITGB6/ITGB8/ITGB1) were specifically enriched in CAde and CSCC, respectively." (PMID 37879219, 2023). "Our results demonstrated the complementary expression of ITGB2 and ITGB6 in SCLC and LUAD suggesting their use as markers for these cancer subtypes and supporting the formation of different integrin heterodimer receptors in SCLC and LUAD." (PMID 37215577, 2023). "Thus, ITGB6 represents not only a valuable prognostic factor in OSCC, but also an attractive target for therapy and diagnosis (theragnostic) in different cancer entities, including OSCC." (PMID 38890650, 2024).
infection (3 papers, 2024 to 2025). The state of being infected such as from the introduction of a foreign agent such as serum, vaccine, antigenic substance or organism. "We found similar evidence of increased effects among individuals with past infection for one pathogenic protein (ITGB6) elevated with LRTIs, and another (PRDX5) increased with skin and subcutaneous infections." (PMID 39143319, 2024). "Genetic variants that influenced expression of immunologically relevant infection-related proteins, including ITGB6 and TLR5, predicted brain volume loss." (PMID 39143319, 2024). "Knockout of the integrin subunit ITGB6 reduced binding, internalization and infection, which could be restored upon stable expression of ITGB6." (PMID 38658526, 2024).
epithelial neoplasm (1 paper, 2024). A benign or malignant neoplasm that arises from and is composed of epithelial cells. "Due to its functional implications in migration and proliferation of cancerous cells, ITGB6 represents an important target structure for the development of novel strategies for the diagnosis and treatment of epithelial neoplasms." (PMID 38890650, 2024).
ITGB6 also shares sentences with these, for which no sentence is quoted: lung carcinoma (4 papers); diabetic kidney disease (3); idiopathic pulmonary fibrosis (3); pancreatic ductal adenocarcinoma (2); age (1); aging (1); alopecia (1); amelogenesis imperfecta (1); basal cell carcinoma (1); cardiovascular disease (1); fibrosis (1); glioblastoma (1); head and neck cancer (1); Intellectual disability (1); interstitial lung disease (1); intrahepatic cholangiocarcinoma (1); liver cancer (1); metastatic cancer (1); metastatic colorectal cancer (1); myoclonic seizures (1); nasopharyngeal carcinoma (1); neurodegenerative disease (1); osteosarcoma (1); pituitary tumor (1); prostate adenocarcinoma (1); pulmonary diseases (1); pulmonary hypertension (1); Salmonella Infections (1).